KLF4 (KLF transcription factor 4)
Diseases named in the same sentence as KLF4 in open-access papers (continued):
Sharing a sentence is not in itself a finding about the gene and the disease.
epilepsy (4 papers, 2022 to 2025). A brain disorder characterized by episodes of abnormally increased neuronal discharge resulting in transient episodes of sensory or motor neurological dysfunction, or psychic dysfunction. "KLF4 showed different expression patterns in type I and type II focal cortical dysplasia (a cause of drug‐resistant epilepsy)." (PMID 36065764, 2022). "Decreased Klf4 protein levels were found in a PTZ‐kindling mouse model of epilepsy." (PMID 39234952, 2024). "Furthermore, we propose a putative, potential epilepsy therapeutic target, Kruppel‐like factor 4 (KLF4)." (PMID 36065764, 2022). "Therefore, exploring the relationship between KLF4 and epilepsy will help to clarify the pathogenesis of epilepsy and discover new therapeutic targets." (PMID 36065764, 2022). "In the next section, we focus on the involvement of KLF4 in neuroinflammation, apoptosis, neurogenesis and autophagy and provide relevant evidence to suggest exploration of the relationship between KLF4 and epilepsy." (PMID 36065764, 2022). "The regulatory effect of KLF4 on neuronal differentiation may improve the glial state of the brain in patients with epilepsy." (PMID 36065764, 2022). "The KLF4‐mediated improvement of neuroinflammation has a positive effect in epilepsy." (PMID 36065764, 2022). "Nonetheless, our understanding of the involvement of Klf4 in seizure disorders remains unclear." (PMID 39234952, 2024). "Additionally, investigating the function of Klf4 in other seizure models, such as genetic models or chronic epilepsy models, could provide a broader understanding of its role in epilepsy pathophysiology." (PMID 39234952, 2024). "Furthermore, KLF4 may be involved in the regulation of mossy fibre sprouting and abnormal migration and integration of neurons during the formation of epilepsy." (PMID 36065764, 2022). "However, further study of the mechanism of KLF4 in epilepsy remains to be conducted." (PMID 36065764, 2022). "Therefore, KLF4 is expected to become a potential therapeutic target for epilepsy, providing new ideas for a more in‐depth understanding of the molecular mechanism of epilepsy." (PMID 36065764, 2022). "It was confirmed that miR-146a directly binds and downregulates the transcription factor Krüppel-like factor 4 (KLF4) to activate STAT3 and mediate epilepsy seizures by affecting synaptic plasticity in the pentylenetetrazole-kindling mouse model of epilepsy." (PMID 37213914, 2023).
gastric tumors (4 papers, 2012 to 2020). "Changes in the expression of KLF4 also can be site specific, being upregulated in cancers of the breast, skin, and lung, but attenuated in colon and gastric tumors." (PMID 23006636, 2012).
intestinal tumors (4 papers, 2009 to 2021). "For example hemizygous KLF2 mice have altered atherosclerotic risk and haploinsufficiency of KLF4 results in increased intestinal tumor formation." (PMID 20454664, 2010). "Interestingly, KLF4 promoter activity is inhibited by Notch, which controls goblet cell differentiation in mouse GI tract, when Notch signaling suppresses KLF4 expression to support intestinal tumors and CRC progression." (PMID 20119532, 2009).
invasive breast carcinoma (4 papers, 2014 to 2020). A carcinoma that infiltrates the breast parenchyma. "Additionally, EGFR and pEGFR proteins are highly expressed in invasive breast cancer and are associated with worse overall survival rates, while high KLF4 is associated with improved survival outcomes." (PMID 32552913, 2020). "Immunohistochemistry for Oct4, Sox2, Nanog, Bmi1, and Klf4 was performed in 319 cases of invasive breast cancer." (PMID 28422735, 2017). "Initially, KLF4 was identified as a transforming oncogene in oral squamous epithelia and subsequently, increased expression of KLF4 was found in ductal carcinoma in situ of the breast and invasive breast cancers when compared to normal breast epithelium." (PMID 24429391, 2014). "Actually, deregulation of miR‐204, miR‐200c, miR‐34a, and miR‐10b simultaneously could significantly reduce the survival rate of breast invasive carcinoma via up‐regulation of OCT4, SOX2, KLF4, c‐MYC, NOTCH1, SNAI1, ZEB1, and CDH2 and down‐regulation of CDH1." (PMID 30710426, 2019).
invasive ductal carcinoma (4 papers, 2015 to 2025). "Nuclear localization of KLF4 contributes to malignant transformation of epithelial cells and is correlated with poor outcome in patients with early‐stage infiltrating ductal carcinoma." (PMID 40066228, 2025). "One example is the Kruppel-like transcription factor KLF4/GKLF whose nuclear localization is a prognostic factor of an aggressive phenotype in the early-stages of infiltrating ductal breast carcinoma." (PMID 25779659, 2015). "Furthermore, tissue arrays of 183 breast invasive ductal carcinoma and 10 adjacent normal tissue specimens were examined by IHC with anti‐KLF4 and anti‐PARP1, and visualized by DAB staining." (PMID 33231937, 2020). "Furthermore, increased nuclear KLF4 expression is considered to be a marker of an aggressive phenotype in early-stage infiltrating ductal carcinoma." (PMID 27323810, 2016). "To further solidify our hypothesis of an increased KLF4α/KLF4(FL) ratio in tumors, we used a matched pair RNA sample from an invasive ductal carcinoma and adjacent normal tissue." (PMID 27323810, 2016).
metastatic tumors (4 papers, 2013 to 2024). "Notably, the activities of Jnk1 that are up-regulated upon loss of Klf4 function may offer a therapeutic avenue to metastatic disease, a notion that warrants further investigation." (PMID 23451207, 2013). "We also detected the expression of KLF4 in metastatic tumor tissues located in the trachea and main bronchus from 12 cases with NSCLC by immunohistochemistry." (PMID 31969824, 2019). "we looked at the expression of KLF4 between primary and metastasis, KLF4 in the endothelial cells of metastatic tumors is significantly higher compared to primary, which implies that KLF4 may be a specific senescence driver in the endothelial cells." (PMID 38951874, 2024). "Firstly, we performed the TF enrichment analysis between primary tumors and metastatic tumors, and finally, seven TFs were identified as differentially expressed TFs, including CBX2, CDX2, FOXA2, KLF4, NANOG, NCAPG, and TFAP2A, which was demonstrated in a heatmap and a volcano plot." (PMID 38702698, 2024).
myocardial ischemia (4 papers, 2016 to 2025). A disorder of cardiac function caused by insufficient blood flow to the muscle tissue of the heart. "Future investigations should incorporate animal models or clinical samples to assess the expression of KLF4 in the context of myocardial ischemia-reperfusion injury." (PMID 40471885, 2025). "In the present study, we investigated a novel pathway, Kruppel-like factor 4 (KLF4)/Mzb1, in the protection of puerarin against ER stress and myocardial injury induced by myocardial ischemia." (PMID 39206261, 2024).
non-Hodgkin lymphoma (4 papers, 2020 to 2025). Distinct from Hodgkin lymphoma both morphologically and biologically, non-Hodgkin lymphoma (NHL) is characterized by the absence of Reed-Sternberg cells, can occur at any age, and usually presents as a localized or generalized lymphadenopathy associated with fever and weight loss. "We have recently reported that YY1 and KLF4 play a role in non-Hodgkin lymphoma (NHL) and that the expression of KLF4 is regulated by YY1." (PMID 33194748, 2020). "Kenpaullone, a commonly used KLF4 inhibitor in basic study, has been shown to significantly downregulate the mRNA and protein levels of KLF4 in various models, including canine mammary tumor,non-Hodgkin lymphoma and autoimmune arthritis." (PMID 40265156, 2025). "Although most of the studies on KLF4 have focused on epithelial tumours, several studies have investigated the role of KLF4 in B cells and B cell malignancies and indicated that it is a tumour suppressor in non-Hodgkin’s lymphoma and a potential biomarker for inferior overall survival." (PMID 35177016, 2022). "Therefore, as a whole, the results described the participation of miR-7 with KLF4 and YY1 in the context of non-Hodgkin’s lymphoma, which was consistent with what was reported in other types of cancer." (PMID 36012357, 2022).
schizophrenia (4 papers, 2016 to 2025). A major psychotic disorder characterized by abnormalities in the perception or expression of reality. "Although KLF4 has been associated with schizophrenia and reported to be down-regulated in patients, it was not expressed in Exc_L2-3 in our dataset." (PMID 40053590, 2025). "Cultured cells, mouse cortex, or striatum was harvested, RNA extracted and RT-PCR conducted for several schizophrenia candidate genes: IL-6, Gad1, Nanog, KLF4, Reln, and Bdnf9a." (PMID 31185023, 2019). "The next most significant gene expression change was KLF4 (kruppel-like factor 4), which is reduced by a similar amount in schizophrenia (50% p<0.01, FDR<0.1)." (PMID 27992436, 2016). "We found significantly down regulated expression of NR4A1 (Nurr 77) and KLF4 mRNAs in people with schizophrenia compared to controls, by both NGS and qPCR (p = or <0.01)." (PMID 27992436, 2016). "This study presents evidence for down-regulation of the nuclear receptors NR4A1, NR4A2, RXRB, and KLF4 mRNAs in the DLPFC in schizophrenia and evidence of reduced RARG and RXRG expression in females with schizophrenia." (PMID 27992436, 2016). "We confirmed the edgeR results using a different analysis program, DESeq2, which also found NR4A1 and KLF4 as the most significantly differentially expressed genes with decreases in schizophrenia similar to that found with edgeR (51% and 47%, respectively)." (PMID 27992436, 2016). "This study reports significant changes in the nuclear receptors NR4A1, NR4A2, and RXRB and KLF4 in schizophrenia and provides further evidence of a role for the nuclear receptors in the disease process." (PMID 27992436, 2016). "We have also found KLF4 to be differentially expressed in schizophrenia compared to controls." (PMID 27992436, 2016).
stomach adenocarcinoma (4 papers, 2016 to 2023). "To better define their correlation, we analyzed the expression levels of KLF4 and MUC2 from TCGA stomach adenocarcinoma database." (PMID 27277677, 2016).
ulcerative colitis (4 papers, 2022 to 2026). An inflammatory bowel disease involving the mucosal surface of the large intestine and rectum. "This study highlights a pro-inflammatory role for KLF4 in a model of ulcerative colitis and shows that the pro- or anti-inflammatory roles for KLF4 are cell-type and tissue specific." (PMID 40534851, 2025). "In ulcerative colitis (UC) patients, KLF4, CFTR, BMP2, TLR2 showed significantly lower expression in UC-associated cancer." (PMID 35733095, 2022).
Ureteral obstruction (4 papers, 2015 to 2024). Obstruction of the flow of urine through the ureter. "The hypermethylation of the KLF4 promoter accompanied by a decrease in KLF4 expression were observed in mice subjected to unilateral ureteral obstruction (UUO) and in HK-2 cells stimulated with transforming growth factor (TGF)-β1." (PMID 25892014, 2015). "In two in vivo models of unilateral ureteral obstruction, a decrease in KLF4 expression was observed and, indicating that KLF4 has anti-fibrotic action in the kidney." (PMID 26617530, 2015). "In unilateral ureteral obstruction (UUO) mice as a model of renal interstitial fibrosis, a decrease in KLF4 expression was observed, indicating that KLF4 has antifibrotic action in the kidney." (PMID 29747407, 2018).
acute lung injury (3 papers, 2016 to 2023). A condition of lung damage that is characterized by bilateral pulmonary infiltrates (pulmonary edema) rich in neutrophils, and in the absence of clinical heart failure. "In addition, miR-34a expression in lung macrophages was increased in a model of LPS-induced acute lung injury (ALI); miR-34a overexpression could promote the polarization of pro-inflammatory M1 phenotype and exacerbated ALI and inflammation by targeting kruppel-like factor 4 (KLF4)." (PMID 37138859, 2023).
autoimmune disease (3 papers, 2020 to 2025). A disorder resulting from loss of function or tissue destruction of an organ or multiple organs, arising from humoral or cellular immune responses of the individual to their own tissue constituents. "KLF4 expression has multitude of effects on various neurologic and autoimmune diseases including EAE/MS." (PMID 32165410, 2020). "Understanding the molecular mechanisms by which KLF4 modulates immune cell fate and function not only enhances our grasp of innate immunity but also opens promising avenues for therapeutic intervention in inflammatory diseases, autoimmune disorders, and tissue repair strategies." (PMID 40831570, 2025).
Chordoid Meningioma (3 papers, 2018 to 2022). A WHO grade II, usually recurring meningioma characterized by the predominance of tissues that are histologically similar to chordoma. "Genetically, previous studies found that chordoid meningiomas had sparce NF2, TRAF7, KLF4, SMO, AKT1 and SMARCB1 mutations common to non-chordoid meningioma." (PMID 35440040, 2022). "Together, the mutations in TRAF7, KLF4, AKT1, and VHL genes were mutually exclusive and occurred in 64.7% of the well-differentiated chordoid meningiomas from ED group #3." (PMID 31963394, 2020). "Whether KLF4 and/or the progesterone receptor that appears to be highly expressed in secretory and chordoid meningioma (MM Georgescu, unpublished observations) play a role in NHERF1 upregulation remains to be investigated." (PMID 29983887, 2018).
Co-infection (3 papers, 2012 to 2024). "Co-infection of utricles with adenoviral vectors separately encoding Oct3/4, Klf4, Sox2, and the degradation-resistant T58A mutant of c-Myc (c-MycT58A) triggered significant levels of supporting cell S-phase entry as assessed by continuous BrdU labeling." (PMID 23119091, 2012). "For genes including: IFNGR2, IL13RA1 and KLF4, little changes were identified in co-infections when compared to un-infected persons." (PMID 23028845, 2012). "EGR1, KLF4, and GPR56 were selected in the case of HIV/HCV co-infection vs the HCV mono-infection." (PMID 23028845, 2012).
colonic adenomas (3 papers, 2007 to 2025). "There is strong evidence that in colonic adenomas and carcinomas reduction of protein and mRNA level of Klf4 is observed in comparison with normal colonic tissues." (PMID 29564063, 2018).
colorectal adenocarcinoma (3 papers, 2021 to 2022). The most common type of colorectal carcinoma. "The cBioPortal database was used to analyze the mutations of seven genes, which showed that E2F3, ETS2, HLF, HSF4, KLF4, MEIS2, and TCF7L1 were altered in 8, 8, 6, 6, 5, 9, and 6% of 524 colorectal adenocarcinoma patients separately." (PMID 34603375, 2021). "In addition, we found that three (CDX1, CDX2, and KLF4) of the four transcription genes (CDX2, KLF4, CDX1, and ELF3) with low expression in CSCC also showed low expression in colorectal adenocarcinoma, while ELF3 achieved the opposite result in colorectal adenocarcinoma." (PMID 35194959, 2022).
cyst (3 papers, 2012 to 2023). A sac-like closed membranous structure that may be empty or contain fluid or amorphous material. "Furthermore, mutational analysis of driver genes, such as KRAS, GNAS, or KLF4, as well as miRNA sequencing and cyst fluid telomere fusion status seem to allow the discrimination of high-risk IPMN from low risk lesions." (PMID 36611137, 2023). "We found that the efficiency of lumen-cyst formation was significantly reduced by siRNA and shRNA, suggesting that KLF4 is essential for cell polarity formation in the 3D culture of Caco-2 cells." (PMID 22384261, 2012). "However, induction of KLF4 expression in LS174T cells significantly increased the chances of cyst formation in 3D culture, indicating that KLF4 indeed enhances cell polarity and thus facilitates cyst formation in 3D formation assay." (PMID 22384261, 2012). "In order to investigate the role of KLF4 in regulating cell polarity, we generated a three-dimensional (3D) epithelial cyst formation assay for Caco-2 cells, in which the morphological structure of cyst and apical-basolateral cell polarity can be examined in vitro." (PMID 22384261, 2012).
ductal carcinoma in situ (3 papers, 2014 to 2024). "For instance, the malignant progression of ductal carcinoma in situ (DCIS) is driven by the overexpression of KLF4." (PMID 39135777, 2024). "This notion is supported by the work demonstrating that a harsh microenvironment in ductal carcinoma in situ (DCIS) of breast cancer selects for the “Warburg Effect” phenotype through transcriptional activation of KLF4, which results in aggressive clonal expansion." (PMID 38300633, 2024).
emphysema (3 papers, 2012 to 2022). "Quantification of KLF4 and KLF2 staining data in these tissue sections suggest that in normal lung, the level of KLF2 is relatively lower than KLF4, in contrast, in emphysema and COPD tissue sections, the levels of KLF2 is higher than KLF4." (PMID 36425528, 2022). "Quantification showed that KLF4 expression was barely detectable in lungs from patients with emphysema and COPD, while the expression level of KLF2 clearly increased." (PMID 36425528, 2022).
follicular lymphoma (3 papers, 2019 to 2025). Follicular lymphoma is a form of non-Hodgkin lymphoma characterized by a proliferation of B cells whose nodular structure of follicular architecture is preserved. "Interestingly, we found that 69% of follicular lymphomas were positive for KLF4, and 65% were positive for YY1, while for DLBCL, KLF4 expression was found in 88% of samples and YY1 expression in 65% of samples." (PMID 31040909, 2019). "We corroborated our results in cell lines, in a TMA from NHL patients including DLBCL and follicular lymphoma subtypes, in where we analyzed miR-7 by ISH and YY1 and KLF4 using IHC." (PMID 33194748, 2020). "The results for follicular lymphoma show that KLF4 vs miR-7 have a negative correlation (r=-0.5229, p=0.0180), and miR-7 vs YY1 also have a negative correlation (r=-0.4248, p=0.0385)." (PMID 33194748, 2020). "Therefore, our results strongly suggest that there is a significant negative correlation between miR-7 expression and that of YY1 or KLF4 in DLBCL and follicular lymphoma." (PMID 33194748, 2020).
fungal infections (3 papers, 2016 to 2018). "The transcription factor Krüppel-like factor 4 (KLF4) was identified as important player in the immune response to fungal infections." (PMID 27346433, 2016). "In consequence, we sought to analyse the possible regulatory role of KLF4 in the transition from innate to acquired immunity during fungal infections." (PMID 27346433, 2016). "The NMT1/2 and MetAP2 genes’ targeting miR-132-5p was found to be associated with fungal infection of human dendritic cells with Candida albicans and Aspergillus fumigatus and regulates immune responses through the interactions with FKBP1B, KLF4, and SPN genes." (PMID 29579063, 2018). "KLF4 may influence the Th1/Th2 balancing via IL6 and thereby be a key regulator in fungal infections." (PMID 27346433, 2016).
germ cell tumor (3 papers, 2016 to 2022). A benign or malignant, gonadal or extragonadal neoplasm that originates from germ cells. "Moreover, we confirmed that LTR5_Hs were preferentially bound by KLF4, NANOG, POU5F1, and TFAP2C in naïve ESCs, by TFAP2C in PGCLCs, and by SOX17 in a germ cell tumor cell line using publicly available ChIP-Seq datasets." (PMID 35551519, 2022).